PAX8 (paired box 8)
Diseases named in the same sentence as PAX8 in open-access papers (continued):
Sharing a sentence is not in itself a finding about the gene and the disease.
glioblastoma (2 papers, 2014 to 2022). The most malignant astrocytic tumor (WHO grade IV). "The cause for the increased PAX8 expression in glioblastomas is unknown." (PMID 24602166, 2014). "Three glioblastomas showed a moderate PAX8 expression level (from 5- to 10-fold higher), three had a low PAX8 expression level (from 3- to 5-fold higher)." (PMID 24602166, 2014). "The PAX8 expression was 10-fold higher in 27/40 (68%) glioblastomas and the two low-grade astrocytomas typed as PAX8-positive by IHC." (PMID 24602166, 2014). "Our data include glioblastoma and malignant meningioma amongst the cancers with a high incidence of PAX8-positive tumours." (PMID 24602166, 2014). "In earlier studies involving PAX8 and glioblastomas, we found increased PAX8 expression in tumours using a small panel of 14 telomerase-positive tumours and cell lines." (PMID 24602166, 2014). "The expression of PAX8 was also studied in glioblastoma, but with contradictory results." (PMID 35806410, 2022). "Seventy-two percent of glioblastomas were PAX8-positive (80% telomerase, 73% NDTMM, and 44% ALT)." (PMID 24602166, 2014). "We found that PAX8 acted as a pro-survival factor for glioblastomas." (PMID 24602166, 2014). "PAX8 is increased in the majority of glioblastomas and promoted cell survival." (PMID 24602166, 2014). "PAX8-positive glioblastomas were present in all the telomere maintenance mechanism groups, but a higher prevalence was observed in the telomerase-positive (80%) and NDTMM-positive (73%) tumours compared with the ALT-positive tumours (44%; P = 0.007 and P = 0.043, respectively)." (PMID 24602166, 2014). "The majority of the PAX8-positive glioblastomas possessed at least 60% PAX8-positive tumours cells." (PMID 24602166, 2014). "In adult tissues, the PAX genes are proposed to be important for maintaining stem cells; therefore, the increased PAX8 expression in glioblastomas may be indicative of an early cell lineage." (PMID 24602166, 2014). "PAX8-positive tumours were frequently observed in 72% (86/120) of the glioblastoma samples." (PMID 24602166, 2014). "Therefore, in telomerase-positive glioblastomas, the PAX8 expression may play an important part in the immortalisation process by regulating telomerase activity." (PMID 24602166, 2014). "The frequency of PAX8-positive tumours was similar between the telomerase- and NDTMM-positive tumours and was lower in the ALT-positive glioblastomas (44% of tumours, of which only half showed strong PAX8 immunostaining)." (PMID 24602166, 2014). "Furthermore, TAZ is reduced in proneural glioblastomas, which are usually ALT-positive tumours and those with reduced PAX8 positivity in the current study." (PMID 24602166, 2014). "But PAX8 expression was not restricted to telomerase-positive glioblastomas." (PMID 24602166, 2014). "Glioblastomas typed as PAX8-negative had no PAX8-positive tumour cells present." (PMID 24602166, 2014).
Glucose intolerance (2 papers, 2019). Glucose intolerance (GI) can be defined as dysglycemia that comprises both prediabetes and diabetes. "Pax8 +/- mice exhibited mild glucose intolerance as compared to Wt mice even when values were corrected for basal glucose levels." (PMID 31518338, 2019). "Consistent with this premise, we found 2 mutations within the PAX8 gene, PAX8P25R and PAX8T356M in 2 independent families, in which females harboring one of these mutations developed GDM and glucose intolerance during pregnancies." (PMID 31817798, 2019). "Unexpectedly, Pax8+/− females remained normoglycemic and did not suffer glucose intolerance throughout pregnancy." (PMID 31817798, 2019). "Insulin levels during an oral glucose tolerance test (OGTT) were similar in Pax8 +/- mice, suggesting that glucose intolerance in these animals is not due to major defects in glucose-stimulated insulin secretion." (PMID 31518338, 2019).
head and neck squamous cell carcinoma (2 papers, 2021 to 2025). A squamous cell carcinoma that arises from any of the following anatomic sites: lip and oral cavity, nasal cavity, paranasal sinuses, pharynx, larynx, and salivary glands. "Positive PAX8-staining is reported in five of seven ATC cases mimicking primary head and neck squamous cell carcinoma." (PMID 40271195, 2025). "Thus, PAX8 proved to be an excellent marker for follicular epithelial origin, even poorly differentiated ones, to make the differential diagnosis from head and neck squamous cell carcinoma." (PMID 34540435, 2021). "Meanwhile, another study reported that PAX8 staining was positive in 26 (76%) ATC cases, including all 16 squamodisc variants, 7 (58%) giant cell/pleomorphic variants, and 3 (50%) spindled variants, and all head and neck squamous cell carcinomas were negative for PAX8 contrastly." (PMID 40271195, 2025). "In the same study, all the head and neck squamous cell carcinomas had negative results for PAX8." (PMID 34540435, 2021).
Hypertension (2 papers, 2018 to 2025). The presence of chronic increased pressure in the systemic arterial system. "In contrast, hypertension shows that genes like SLC16A7, SPX, and PAX8 are less central, indicating they play a reduced role in the vascular and kidney networks." (PMID 40909129, 2025).
hyperthyroidism (2 papers, 2019 to 2025). Overactivity of the thyroid gland resulting in overproduction of thyroid hormone and increased metabolic rate. "In the present study, compared with Thy-Tet1+/+ mice, Thy-Tet1−/− mice developed hyperthyroidism, accompanied by elevated levels of PAX8, TPO and NIS." (PMID 41152554, 2025).
kidney failure (2 papers, 2018). An acute or chronic condition that is characterized by the inability of the kidneys to adequately filter the blood. "Conditional deletion of Vps34/PI3KC3 in PTCs by Pax8-Cre resulted in early (P7) PTC dysfunction, manifested by Fanconi-like syndrome, followed by kidney failure (P14) and death." (PMID 30237523, 2018).
lymph node metastases (2 papers, 2013 to 2023). "DCAF8 decrease was also marginally associated (p = 0.06) with distal lymph node metastasis, while CHEK1 and PAX8 expressions were significantly correlated with worse overall patients’ survival (p < 0.0001 and p < 0.049, respectively), as evidenced by the relevant Kaplan–Meier curves." (PMID 36831395, 2023).
meningioma (2 papers, 2014 to 2018). A generally slow growing tumor attached to the dura mater. "PAX8-positive cases included one recurrent grade I astrocytoma, one grade II astrocytoma, and one meningioma." (PMID 24602166, 2014). "In the 52 cases of meningioma and astrocytomas grades I and II, three PAX8-positive cases were detected." (PMID 24602166, 2014). "PAX8-positive tumours were also observed in other aggressive tumours in the brain, including all malignant meningiomas (n = 4) and 40% of grade 3 astrocytomas (4/10)." (PMID 24602166, 2014). "The radiologically-determined location of the tumor was consistent with aggressive meningioma; however, this possibility was ruled out because the morphology was not typical of either conventional or papillary subtypes and both of these are usually negative for PAX8 and WT1." (PMID 29960592, 2018).
neuroblastoma (2 papers, 2020). Neuroblastoma (NB) is the most common solid, extracranial childhood tumor. "Using CEN‐tools, we isolated such genes and revealed a subnetwork consisting of a number of transcription factors (TFs) that are known to control tissue differentiation into a specific lineage such as SOX10 in skin, PAX8 in ovary, kidney and endometrium (, and MYCN in neuroblastoma." (PMID 33073517, 2020).
oncocytic tumor (2 papers, 2009 to 2024). "According to their specific gene-expression profiles as well as their mutational status for RAS and PAX8-PPARγ genes, oncocytic tumors should be considered as distinct from the other follicular tumors." (PMID 19893615, 2009).
oncocytoma (2 papers, 2022 to 2024). "Immunohistochemically, oncocytoma is usually positive for EMA, CD117, and PAX8, but negative for CD10, alpha-inhibin and vimentin." (PMID 35220972, 2022).
osteoporosis (2 papers, 2019 to 2023). A condition of reduced bone mass, with decreased cortical thickness and a decrease in the number and size of the trabeculae of cancellous bone (but normal chemical composition), resulting in increased fracture incidence. "Moreover, PAX8 is involved in the progression of diabetic nephropathy by targeting the miR-17-5p/STAT3 axis and osteoporosis by activating the autophagy of osteoblasts via the miR-1252-5p/GNB1 axis." (PMID 36831395, 2023).
ovarian endometriosis (2 papers, 2021 to 2023). A non-neoplastic disorder characterized by the growth of endometrial tissue in the ovaries. "Additionally, for the detection of ectopic endometrial epithelial cells PAX8 demonstrated sensitivities of 100% (8/8) in ovarian endometriosis and of 97.9% (46/47) in extragenital epithelial endometrial cells." (PMID 33477657, 2021). "Furthermore, Pax-8 positive epithelial cells on the ovarian surface and OEIs showed moderate to strong FRA expression, while Pax-8 negative epithelial cells on the ovarian surface and OEIs were negative for FRA, which is supportive of tubal origin of ovarian endometriosis." (PMID 36936232, 2023).
papillary renal cell carcinoma (2 papers, 2023 to 2024). A rare subtype of renal cell carcinoma, arising from the renal tubular epithelium and showing a papillary growth pattern, which typically manifests with hematuria, flank pain, palpable abdominal mass or nonspecific symptoms, such as fatigue, weight loss or fever. "The tumour was positive for PAX8 and negative for TTF-1 indicating the renal origin of the tumour while positivity for AMACR & CK7 confirmed the diagnosis of papillary renal cell carcinoma." (PMID 38265103, 2024).
paraganglioma (2 papers, 2016 to 2022). A benign or malignant neoplasm arising from paraganglia located along the sympathetic or parasympathetic nerves. "Negativity for PAX8 ruled out ccRCC; negativity for chromogramin and synaptophysin ruled out paraganglioma." (PMID 28003924, 2016).
parathyroid adenoma (2 papers, 2024 to 2025). "It is also of note that we had seen PAX8 positivity neither in 4 samples of normal parathyroid nor in 43 parathyroidal adenomas by MSVA-708R, while normal parathyroid was stained strongly by MRQ-50." (PMID 39105782, 2024).
polycystic kidney disease (2 papers, 2021 to 2025). A usually autosomal dominant and less frequently autosomal recessive genetic disorder characterized by the presence of numerous cysts in the kidneys leading to end-stage renal failure. "PAX8 was found to affect the branching shape of a normally developing kidney and be expressed in metastatic renal cell carcinoma (RCC) and polycystic kidney disease." (PMID 34461918, 2021).
Primary hypothyroidism (2 papers, 2021 to 2025). A type of hypothyroidism that results from a defect in the thyroid gland. "Animals with inducible Pax8-Cre–mediated Grp170-KO do develop renal insufficiency, and it is reasonable to entertain the hypothesis that these animals might experience the “euthyroid-sick” syndrome rather than primary hypothyroidism." (PMID 40923318, 2025).
rectal adenocarcinoma (2 papers, 2020 to 2025). "In contrast, the tumor cells in the PTC were positive for TTF-1 and PAX8, but negative for rectal adenocarcinoma marker." (PMID 32375670, 2020). "At her next colonoscopy, a palpable posterior rectal mass was biopsied confirming rectal adenocarcinoma with positive caudal type homeobox 2 (CDX-2) and negative paired box gene 8 (PAX-8)." (PMID 40678160, 2025). "The tumor cells of metastatic rectal adenocarcinoma were positive for gastrointestinal markers CDX2, CK20 and Villin but were negative for TTF-1 and PAX8." (PMID 32375670, 2020).
renal dysplasia (2 papers, 2017 to 2021). Renal dysplasia is a form of renal malformation in which the kidney(s) are present but their development is abnormal and incomplete. "It was found that Pax2 and Pax8 mainly contribute to the development of pronephros and mesonephros and that Pax2 and Pax8 double-null mice fail to generate the nephric duct and have renal dysplasia." (PMID 34205452, 2021).
renal fibrosis (2 papers, 2021 to 2023). A final common manifestation of a wide variety of chronic kidney diseases characterized by glomerulosclerosis and tubulointerstitial fibrosis. "PAX8/HDAC2-/- mice also had reduced renal fibrosis at 28 days." (PMID 33907245, 2021).
renal oncocytoma (2 papers, 2025). "Negative immunoreactivity for pancytokeratin and PAX8 also excluded the diagnosis of renal oncocytoma." (PMID 39568313, 2025).
sarcomatoid carcinoma (2 papers, 2018 to 2025). A malignant epithelial neoplasm characterized by the presence of spindle cells and anaplastic morphologic features. "Mucinous tubular and spindle cell carcinoma is also a biphasic tumor but can be distinguished by its prominent tubular component with extensive branching and interconnecting tubular architecture and is PAX8-, EMA-, CK7-, and AMACR-positive." (PMID 41268216, 2025).
sleep disorder (2 papers, 2024 to 2025). A change from the patient's baseline sleeping pattern, in the hours slept and/or an alteration/dysfunction in the stages of sleep. "We observed 142 associations including at known loci for sleep disorders (e.g. MEIS1, CACNA1C, OLFM4, PAX8 and TCF4)." (PMID 41332830, 2025).
thymic adenocarcinoma (2 papers, 2021 to 2023). "Previous studies on thymic adenocarcinoma showed that most cases were positive for cytokeratin 7 and CD5 and negative for PAX8 and TTF1." (PMID 39790334, 2023). "PAX8, TTF1, c-KIT, and napsin A were negative, indicating thymic adenocarcinoma." (PMID 39790334, 2023).
thyroid adenocarcinoma (2 papers, 2014 to 2021). "In thyroid adenocarcinomas the PAX8/PPAR-γ (peroxisome proliferator-activator receptor gamma 1) fusion protein confers many oncogenic properties, including increased proliferation, decreased apoptosis and the inhibition of wild-type PPAR-γ." (PMID 24602166, 2014).
Ureteral obstruction (2 papers, 2018 to 2023). Obstruction of the flow of urine through the ureter. "To examine whether ureteral obstruction was caused by existence of xenogeneic cells in nephric duct during the development, we generated interspecies chimera by injection of Pax2 and Pax8 double knockout ES cells into Rat blastocyst." (PMID 30327488, 2018). "Urine flow testing revealed that no ureteral obstruction was observed in Pax2 and Pax8 double mutant ESCs injected interspecies chimera." (PMID 30327488, 2018).
urothelial carcinoma of the renal pelvis (2 papers, 2022 to 2025). "Similarly, urothelial carcinoma of the renal pelvis shows expression of INI1/SMARCB1, maybe positive for PAX-8, and tends to occur in older patients." (PMID 40777608, 2025).
uterine cancer (2 papers, 2021 to 2023). Primary or metastatic malignant neoplasm involving the uterine corpus and/or the cervix. "Clinically, positive immunohistochemical staining for PAX8 is widely used to diagnose primary renal cell tumors and mutations are also frequently seen in thyroid, ovarian, bladder, prostate, endometrial, cervical, and uterine cancers." (PMID 34925233, 2021).
adenomyosis (1 paper, 2022). The growth of endometrial tissue inside the muscular wall of the uterine corpus. "In the adenomyosis and control groups, most of the samples exhibited high PAX8 expression in the functional layer of the endometrium (the proportions of high expression: adenomyosis, 86%; control, 60%; p = 0.07)." (PMID 35682653, 2022). "Unlike for the low expression of gene products from hypermethylated PAX8 and WNT5A in adenomyosis, the IHC staining results revealed inconsistent trends in higher protein expression." (PMID 35682653, 2022).
anal adenocarcinoma (1 paper, 2025). "Positive CK20, CDX2, villin, and SATB2 confirmed adenocarcinoma with intestinal differentiation, while PAX8 negativity ruled out ovarian malignancy, concluding that the lymphadenopathy was likely due to metastasis of anal adenocarcinoma." (PMID 41573493, 2025).
angiomatoid fibrous histiocytoma (1 paper, 2024). "Specifically, MAP3K8 and ALK presented PAX8+ papillary proliferations, ESWR1/FUS::ATF1 and EWSR1::YY1 displayed angiomatoid fibrous histiocytoma-like patterns, while SUFU showcased ‘tissue culture’-like spindle cell proliferation." (PMID 39059063, 2024).
appendiceal adenocarcinoma (1 paper, 2019). "The appendiceal adenocarcinoma also showed positive immunoreaction for CK7, CK20, CDX-2, and SATB2 but was negative for estrogen receptor, progesterone receptor, Pax-8, CD56, synaptophysin, and chromogranin A." (PMID 31409389, 2019). "Both the appendiceal adenocarcinoma and malignant components of the OMT stained positive for CK7, CK20, CDX-2, and SATB2 but negative for estrogen receptor, progesterone receptor, and pax-8." (PMID 31409389, 2019).
asthma (1 paper, 2022). "Most of the top eQTM genes have been implicated in lung disease for example PAX8; associated with bronchodilator response in children with asthma, ECHDC3 with obesity and asthma in children, LSP1 with acute lung inflammation, HLA‐DQB1 with asthma and total IgE, and KANSL1 with pulmonary function." (PMID 35344303, 2022).
astrocytomas (1 paper, 2014). "A larger cohort of the low-grade PAX8-positive tumours might show an association with poorer outcomes because in our cohort, the single PAX8-positive grade I astrocytoma was a recurrent tumour." (PMID 24602166, 2014).
Atrophy (1 paper, 2022). Any weakening or degeneration, especially through lack of use. "Our study demonstrates that various kidney diseases with chronic disease course that results in the formation of tubular atrophy and interstitial fibrosis, lead to PAX8 expression in the nuclei of proximal tubules." (PMID 36140438, 2022).
benign ovarian tumor (1 paper, 2020). "The control sample (peritoneum of a patient with a benign ovarian tumor) did not stain for PAX8." (PMID 32008138, 2020).
brain tumours (1 paper, 2014). "A few PAX8-positive cells were identified in the cerebellum between the molecular and the nuclear layer in the two adult brain tumours containing cerebellum tissue." (PMID 24602166, 2014). "In summary, PAX8-positive cells were detected in aggressive brain tumours." (PMID 24602166, 2014).
chromophobe renal cell carcinoma (1 paper, 2023). Chromophobe renal cell carcinoma is a rare subtype of renal cell carcinoma, originating from the intercalating cells of the collecting ducts and macroscopically manifesting as a well-circumscribed, highly lobulated, solid tumor that is usually diagnosed at an early stage. "Immunostaining revealed the tumor cells to be positive for CD10, CD117, and E-cadherin and negative for CK7, and PAX8, leading to the diagnosis of metastatic chromophobe renal cell carcinoma (chRCC) in the liver." (PMID 37560153, 2023).
crescentic glomerulonephritis (1 paper, 2017). A histopathologic term for a pattern of diseases characterized by extensive crescent formation in the glomeruli; patients present clinically with rapid deterioration of renal function, and possible progression to end-stage renal failure within weeks or months. "However, pGR KO and Pax8-Cre GR KO mice appear to differ in that the crescentic glomerulonephritis induced by NTS is clearly worsened in pGR KO and attenuated in Pax8-Cre GR KO mice." (PMID 28852159, 2017).
cystadenoma (1 paper, 2019). A benign or borderline cystic epithelial neoplasm arising from the glandular epithelium. "Mucinous cystadenomas showed more heterogeneous results, in which 71.8% (28/39) and 35.9% (14/39) were expressing CK7 and PAX8, respectively, while 10.3% (4/39) were positive for CK20 and CDX2." (PMID 31771640, 2019).
endocrine tumors of the pancreas (1 paper, 2019). "Furthermore, PAX8 was wrongfully detected in endocrine tumors of the pancreas raising doubts on the authenticity of PAX8 expression in islets." (PMID 31817798, 2019).